G6PD (glucose-6-phosphate dehydrogenase)
Diseases named in the same sentence as G6PD in open-access papers (continued):
Sharing a sentence is not in itself a finding about the gene and the disease.
neurological disorders (3 papers, 2024 to 2026). "Six most prevalent pathogenic G6PD variants in China were screended in children with rare neurological disorders (n = 211) and in controls without neurological involvement (n = 202)." (PMID 41716257, 2026).
psychiatric disorder (2 papers, 2018 to 2019). A disorder characterized by behavioral and/or psychological abnormalities, often accompanied by physical symptoms. "* Contraindications: glucose-6-phosphate dehydrogenase (G6PD) deficiency, pregnancy, breastfeeding (if infant has G6PD deficiency or if G6PD status is unknown), known hypersensitivity to 8-aminoquinolines, history of psychiatric disorder." (PMID 31751320, 2019).
adenocarcinoma (1 paper, 2017). A common cancer characterized by the presence of malignant glandular cells. "Notably, 4 of the glucose metabolism-related genes, GPI, G6PD, PKM2, and GAPDH and 5 of the cell cycle-related genes, ANLN, PTTG1, CIT, KPNA2, and CDC25A, were significantly down-regulated in EGFR m+ adenocarcinomas, and showed a substantial correlation with SUVmax." (PMID 28422979, 2017).
endocrine disease (1 paper, 2022). "In the case of an underlying endocrine disease, in which the hormone involved is known to potentially affect the G6PD expression, the patient should be managed, when possible, by correcting the underlying endocrinopathy." (PMID 36431166, 2022).
gastrointestinal disorders (1 paper, 2017). "Furthermore, primaquine causes gastrointestinal disorders such as nausea, dizziness, and vomiting in both normal and G6PD deficient patients." (PMID 28279180, 2017).
inborn errors of metabolism (1 paper, 2022). An inherited disorder resulting from an enzyme defect in biochemical and metabolic pathways affecting proteins, fats, carbohydrates metabolism or organelle function. "Glucose-6-phosphate dehydrogenase (G6PD) deficiency, which is caused by pathogenic variants of G6PD that result in decreased G6PD activity, is an X-linked inherited inborn error of metabolism that occurs worldwide." (PMID 36212124, 2022).
mitochondrial disease (1 paper, 2020). "Based on our studies, it is conceivable that G6PD deficiency will sensitize cells with mitochondrial disease mutations or to insults that impair ETC activity." (PMID 32483148, 2020).
G6PD also shares sentences with these, for which no sentence is quoted: kidney disease (5 papers); pneumonia (5); Spherocytosis (5); autoimmune hemolytic anemia (4); Down syndrome (4); hemochromatosis (4); Immunodeficiency (4); Wilson disease (4); autism spectrum disorder (3); celiac disease (3); developmental delays (3); gout (3); Hepatic failure (3); hereditary hemolytic anemia (3); porphyria (3); trichomoniasis (3); triple-negative breast carcinoma (3); typhoid fever (3); vasculopathy (3); bone marrow failure (2); breast (2); cardiac arrhythmias (2); chlamydia (2); dengue haemorrhagic fever (2); end-stage renal disease (2); fibrosis (2); food allergies (2); gonorrhea (2); hemolytic-uremic syndrome (2); hereditary stomatocytosis (2).
A further 188 diseases each share a sentence with G6PD in 2 papers or fewer.